VCX3A (variable charge X-linked 3A)
Description:
May mediate a process in spermatogenesis or may play a role in sex ratio distortion.
Synonyms: VCX-8r; VCX-A; VCX3; VCX8R; VCXA
Tractability: No criterion of Open Targets' tractability assessment is met for any kind of drug.
Gene: Protein-coding gene on chromosome X (6,533,618 to 6,535,118, reverse strand). Ensembl gene ENSG00000169059.
Gene Ontology:
Biological process: brain development
Cellular component: nucleolus; nucleus
Homologues: Paralogues in human: VCX (98% identical), VCX3B (97% identical), VCX2 (66% identical), VCY (60% identical), VCY1B (60% identical).
Diseases named in the same sentence as VCX3A in open-access papers:
VCX3A is named in the same sentence as 25 diseases in open-access papers, as found by Europe PMC text mining. Sharing a sentence is not in itself a finding about the gene and the disease. The quoted sentences say what the papers report.
Intellectual disability (7 papers, 2007 to 2023). "CNVs at Xp22.31 encompassing STS and VCX3A are frequently associated with ichthyosis, and sometimes intellectual disability." (PMID 31963867, 2020). "VCX3A was proposed to be involved in cognition on the basis of overlapping Xp22.3 deletions associated with mental retardation in a few males." (PMID 17517138, 2007). "VCX-A and VCX-3A deficiency has been previously shown to be associated with intellectual disability." (PMID 32670353, 2020). "CNVs at Xp22.31 are frequently associated with X-linked ichthyosis and intellectual disability, particularly when the CNVs encompass STS (MIM 300747) and VCX3A (MIM 300533)." (PMID 31963867, 2020). "Among them, NLGN4 is the only gene identified for XLID, along with autism and Asperger syndrome at Xp22.31 and, more than a decade ago, VCX3A was proposed as a candidate gene to account for intellectual disability in this region." (PMID 31963867, 2020). "The presence of the VCX3A gene in XLI patients of normal intelligence and its absence in XLI patients with intellectual disability suggest that a single intact copy of VCX3A is necessary to maintain normal intelligence levels." (PMID 31857824, 2019). "Moreover, a VCX3A promoter deletion has been reported in a XLI case with borderline intellectual disability." (PMID 31857824, 2019). "The VCX3A gene was found to be deleted in patients with intellectual disability, whereas patients with more proximal CNVs, not including VCX3A, displayed normal intelligence." (PMID 31963867, 2020). "The manifestation of intellectual disability in individuals with CNVs encompassing VCX3A appears to be under the influence of incomplete penetrance, because not all male patients with a deletion involving VCX3A display cognitive impairment." (PMID 31963867, 2020).
ichthyosis (4 papers, 2014 to 2023). Disorders of cornification that are characterized by visible scaling and/or hyperkeratosis of most or all of the skin. "The deletion including STS and VCX3A was found in two cases with ichthyosis and/or mental retardation." (PMID 24885232, 2014).
Obesity (2 papers, 2020 to 2022). Accumulation of substantial excess body fat. "For those 12 genes, six of them (DDO, SEPT9, TMEM45B, RXRα, ZNF395 and AHRR) were previously reported to be implicated in the obesity or related diseases and the rest six were novel (PACRG, LINC00494, KLHL4, DTX1, VCX3A and VSTM1)." (PMID 35568907, 2022).
breast carcinoma (1 paper, 2020). "RNA sequencing analysis also indicated that VCX2 might be less frequently expressed in melanoma and breast cancer than other VCX gene family members (VCX and VCX3A)." (PMID 33634013, 2020).
diffuse midline glioma (1 paper, 2025). A diffuse glioma that arises from the midline structures of the central nervous system. "Interestingly, we also noted profound upregulation of VCX3A, which has been reported to regulate the expression of HLA molecules in diffuse midline glioma." (PMID 41408661, 2025).
learning disabilities (1 paper, 2022). "There have been case reports in the literature of individuals with XLI and learning disabilities; in these cases, the genetic deletions tend to be larger, and often encompass the VCX3A (formerly VCXA) and/or NLGN4X genes." (PMID 36479267, 2022).
cancer (1 paper, 2023). A tumor composed of atypical neoplastic, often pleomorphic cells that invade other tissues. "Further, AIWrap identified six new genes (VCX3A, CALHM5, ZMYND10, FOXE1, PLAT, FADD) which could be related to smoking in cancer patients, thus providing an opportunity for identifying previously unknown biological functions." (PMID 37853338, 2023).
VCX3A also shares sentences with these, for which no sentence is quoted: autism (3 papers); cognitive deficits (2); genetic diseases (2); Asperger syndrome (1); auditory neuropathy (1); Azoospermia (1); focal epilepsy (1); hearing loss (1); hereditary neuropathy with liability to pressure palsies (1); hyperlipidemia (1); hypogonadotropic hypogonadism (1); infantile spasms (1); Infertility (1); Leri-Weill syndrome (1); melanoma (1); microcephaly (1); Strabismus (1); X-linked ocular albinism (1).